TPO (thyroid peroxidase)
Diseases named in the same sentence as TPO in open-access papers (continued):
Sharing a sentence is not in itself a finding about the gene and the disease.
autoimmune thyroid disease (continued). "We present here refined models of a membrane-bound TPO, providing a much-needed platform for structurally interpreting epitope data and highlighting new avenues for investigation of the breakdown of immune tolerance to TPO in thyroid autoimmune disease." (PMID 26623656, 2015). "Plasma antithyroid peroxidase (anti-TPO) and anti-thyroglobulin antibodies (anti-Tg) are widely used in the diagnosis of autoimmune thyroiditis." (PMID 26798549, 2015). "The prevalence of thyroid autoimmunity (defined as serum anti-TPO Ab titre >35 IU/mL) was found to be 28.0 (19.2–36.8)%." (PMID 25653881, 2015). "These autoimmune thyroid diseases are characterized by elevated serum antibodies directed against thyroid-specific antigens like thyroid peroxidase (TPO) and thyroglobulin (Tg)." (PMID 25653881, 2015). "TPO is a major autoantigen in autoimmune thyroid diseases (AITDs), encompassing Hashimoto’s thyroiditis and Graves’ disease." (PMID 26623656, 2015). "Our findings appear to demonstrate such an effect: It appears that most of thyroid autoimmunity effect was due to positive TPO antibody status." (PMID 25975563, 2015). "The prevalence of thyroid autoimmunity in vitiligo patients (anti-TPO antibodies serum titre ≥35 IU/mL) at the study site was found to be 28% (19.2–36.8%)." (PMID 25653881, 2015). "The present state of hypothyroidism with a high titre of anti-TPO antibody was suggestive of autoimmune thyroiditis." (PMID 25547669, 2014). "Antithyroid peroxidase and antithyroglobulin antibodies (anti-TPO and anti-TG, respectively) were detected as markers for thyroid autoimmunity." (PMID 25237328, 2014). "Measuring circulating antibodies to thyroglobulin to detect autoimmune thyroid disease is uncommon measurement of anti-TPO that gives reliable information about autoimmune thyroid disease." (PMID 24808970, 2014). "In HT, the immune system produces autoantibodies to thyroid-specific antigens, considering that thyroglobulin (Tg) and thyroperoxidase (TPO) are the two primary antigens in thyroid autoimmunity." (PMID 25328756, 2014). "TPO is an important enzyme in the synthesis of thyroid hormone and anti-TPO antibodies are helpful in diagnosing and estimating the clinical course of autoimmune thyroid diseases." (PMID 24808970, 2014). "Autoimmune thyroiditis with detectable anti-thyroid peroxidase antibody after autologous transplantation has been reported in an MM patient, as have exacerbations of underlying autoimmune diseases." (PMID 24876970, 2014). "Although the clinical significance of these antibodies in celiac disease is still unclear, there is probably a higher propensity for thyroid autoimmunity in children with positive TPO markers." (PMID 24592326, 2014). "This clinical picture along with a highly positive titre of anti-TPO (microsomal) antibody is compatible with the diagnosis of autoimmune thyroiditis." (PMID 25547669, 2014). "Of 100 pregnant patients with previous recurrent miscarriage, thyroid autoimmunity (anti-TPO >34 U/ml) was found in 31% (P=0.031) and subclinical hypothyroidism was observed in 27% (P=0.74) of the cases." (PMID 23802061, 2013). "Although TPO-Ab and Tg-Abs are both markers of thyroid autoimmunity, it has been argued that TPO-Ab is more relevant in the prediction of thyroid dysfunction." (PMID 23691429, 2013). "In autoimmune thyroid disease, it appears that Tg-Ab and TPO-Abs are more a response to thyroid inflammation than the actual cause as evidenced by their polyclonality and their failure to induce disease when transferred to animal models." (PMID 23691429, 2013). "Se supplementation decreased inflammatory activity in patients with autoimmune thyroiditis, and the reduction of titres of anti-TPO antibodies was correlated with serum levels of Se." (PMID 22400102, 2012).
autoimmune thyroid disease (continued). "Autoimmune thyroid disease was defined as raised titre of at least one anti-thyroid antibody [anti-thyroid peroxidase (anti-TPO), anti-thyroglobulin (anti-Tg) and/or anti-TSH-receptor (anti-TSH-R) antibodies]." (PMID 23244563, 2012). "Thyroid functions (fT3, fT4, and TSH) and thyroid autoimmunity (anti-thyroid peroxidase (anti-TPO), and anti-thyroglobulin (anti-Tg) antibodies) were investigated in both groups." (PMID 23118611, 2012). "It has been reported that the serum of patients with RTH is free of auto-antibodies against thyroglobulin (Tg) and thyroid peroxidase (TPO), except in rare cases where coincidental autoimmune thyroiditis is also present." (PMID 22937287, 2011). "The 2 groups were compared for age, duration of diabetes, thyroid autoimmunity, anti-TPO and anti-Tg autoantibodies." (PMID 22029731, 2011). "In adults, selenium supplementation decreases thyroid peroxidase antibody (TPO Ab) concentrations in patients with autoimmune thyroiditis (AIT)." (PMID 20526530, 2010). "All patients had evidence of active anti-thyroid autoimmunity in their serum samples but the complete panel of anti-thyroid Abs (anti-TG, anti-TPO, and anti-TSH receptor Abs) was assessed in seven patients only (Patient 1, 3, 5, 10, 11, 12, and 13)." (PMID 20426819, 2010). "Anti-TPO aAbs are invaluable markers of thyroid autoimmune response and have been shown to exert both in vitro and in vivo cytotoxic functions such as C3 complement activation and antibody-dependent cell-mediated cytotoxicity (ADCC)." (PMID 20145622, 2010). "Of the women in our sample, 85.22% had normal values for TPO-Ab and Tg-Ab and 14.77% had results revealing the presence of autoimmune diseases of the thyroid." (PMID 19939287, 2009). "We found that 177 (14.77%) of the pregnant women were positive for TPO-Ab and Tg-Ab, indicating a level of autoimmune diseases of the thyroid in our population that is very similar to that found in other studies." (PMID 19939287, 2009). "In conclusion, of the 1198 pregnant women resident in the Aragon region of Spain analyzed in our study, 85.22% had normal TPO-Ab and Tg-Ab values and 14.77% tested positive for autoimmune diseases of the thyroid." (PMID 19939287, 2009). "Clinical autoimmune thyroid disease was diagnosed subsequent to positive anti-TPO results in 4 out of 24 (17%), 2 in the case and 2 in the control group." (PMID 16526964, 2006). "The aim of the present review is to summarize the current knowledge regarding the localization of the immunodominant region recognized by human thyroid peroxidase-specific autoantibodies generated during the development of autoimmune thyroid diseases." (PMID 15769293, 2005). "Among these autoantigens which are targeted by autoantibodies during the development of autoimmune thyroid diseases, thyroid peroxidase is a major player." (PMID 15769293, 2005). "Additionally, IgE anti-TPO levels correlated with IgG anti-TPO levels supporting the notion that CSU patients are at risk for autoimmune thyroid diseases and thyroid dysfunction." (PMID 40782271, 2025). "Furthermore, the prevalence of thyroid autoimmunity, including elevated anti-TPO levels, rises with age, making this population particularly relevant for studying the interplay between thyroid autoimmunity and renal health." (PMID 40937419, 2025). "However, our study uniquely emphasizes the relationship between anti-TPO and systemic inflammatory markers like hsCRP, providing evidence that thyroid autoimmunity has implications beyond the thyroid gland itself." (PMID 39902025, 2025). "Autoimmune thyroiditis (AIT), primarily encompassing Hashimoto’s thyroiditis (HT), is an organ-specific autoimmune thyroid disease characterized by thyroidal lymphocyte infiltration and elevated thyroid peroxidase antibody (TPO-Ab) or thyroglobulin antibody (TG-Ab) levels." (PMID 40909293, 2025).
autoimmune thyroid disease (continued). "The most common autoimmune marker was anti-nuclear antibody (ANA) (22/36, 61%), followed by lupus anticoagulant (15/30, 50%) and any one marker of autoimmune thyroiditis, namely anti-thyroid peroxidase, anti-thyroglobulin, or anti-TSH-receptor antibody (16/37, 43%)." (PMID 40313931, 2025). "Autoantibody screening is useful in suspected cases, with common markers including thyroid peroxidase antibodies for autoimmune thyroid disease, anti-IA2 and anti-insulin antibodies for type 1 diabetes, and 21-hydroxylase antibodies for autoimmune Addison’s disease." (PMID 40951041, 2025). "Our findings do not support a significant role of the TPO rs1126797 polymorphism in conferring susceptibility to autoimmune thyroiditis in the studied Caucasian Polish population." (PMID 40650076, 2025). "Thyroid autoimmunity is thought to influence pregnancy outcomes through immune-mediated mechanisms, where the presence of TPO-Ab and TgAb may affect placental function, leading to inadequate immune tolerance and increased risk of complications." (PMID 41503315, 2025). "The condition is frequently asymptomatic but has been associated with adverse metabolic, cardiovascular, and neuropsychiatric outcomes, particularly when accompanied by thyroid autoimmunity, as evidenced by positive anti-thyroid peroxidase (anti-TPO) antibodies." (PMID 40671987, 2025). "One such theory suggests that autoimmune mechanisms, mediated by antibodies such as anti-thyroid peroxidase (anti-TPO) and anti-thyroglobulin (anti-Tg), which are typically present in autoimmune thyroiditis, may impact the inner ear." (PMID 41155780, 2025). "Anti-TPO reflects localized thyroid autoimmunity, while hsCRP provides insight into systemic inflammation that may extend beyond the thyroid gland." (PMID 39902025, 2025). "Anti-thyroid peroxidase antibodies (TPO-Ab) are detectable in almost all patients with autoimmune thyroid disease or Hashimoto’s thyroiditis (HT) but may also be present in healthy individuals." (PMID 40927297, 2025). "Furthermore, autoimmune thyroid diseases, particularly the presence of thyroid autoantibodies such as anti-thyroid peroxidase and anti-thyroglobulin, have been reported to be significantly associated with moyamoya-like vasculopathy." (PMID 41441210, 2025). "Age was inversely correlated with anti-GAD and anti-islet (r = −0.31, p < 0.001 for both) and positively correlated with anti-TPO (r = 0.36, p < 0.001), suggesting that islet-specific autoimmunity predominates at younger ages, while thyroid autoimmunity becomes more prevalent with aging." (PMID 41008668, 2025). "The relationship between ID and thyroid autoimmunity may be attributed to changes in the antigenicity of TPO, as well as the reduced activity of TPO in the context of Fe deficiency." (PMID 40071251, 2024). "The prevalence of TPO antibodies 3 months after acute infection was 15.7% in COVID-19 survivors compared to 7.7% in age- and sex-matched controls, suggesting a role for COVID-19 in eliciting thyroid autoimmunity." (PMID 39450181, 2024). "Thyroid autoimmunity may result from the formation of autoantibodies that target different thyroid antigens, including thyroglobulin (TG), thyroid peroxidase (TPO), or more importantly, TSH receptor." (PMID 39707289, 2024). "The diagnosis of autoimmune thyroid disease is often supported by the presence of specific autoantibodies targeting thyroid antigens, such as anti-thyroid peroxidase antibodies (anti-TPO Ab), thyroglobulin antibodies (anti-Tg Ab), and thyroid-stimulating hormone receptor antibodies (TSH Rs Ab)." (PMID 39221289, 2024). "Autoimmune thyroiditis was considered present if anti-thyroid peroxidase and anti-thyroid antibody titer exceeded twice the upper limit of the normal range (34 microIU/mL in the case of ATPO and 11 IU/mL in the case of ATG), so the absolute antibody titer was not used for statistical analysis." (PMID 39336427, 2024).
autoimmune thyroid disease (continued). "Autoantibodies to TPO are commonly seen in autoimmune thyroid diseases such as Hashimoto’s disease." (PMID 39936155, 2024). "This could potentially lead to autoimmune thyroid diseases characterized by the production of autoantibodies against thyroid peroxidase (TPO) and thyroglobulin (Tg)." (PMID 39776440, 2024). "Indeed, thyroid peroxidase is a major autoantigen in thyroid autoimmunity and a key player against oxidative stress." (PMID 37246981, 2023). "Finally, autoimmune thyroiditis and anti-TPO are commonly observed following transplantation, cancer treatment with checkpoint inhibitors, and in many autoimmune diseases; this information can be used to argue against an infection-specific mechanism." (PMID 36752204, 2023). "Patients with other types of autoimmune thyroid diseases may also have elevated anti-TPO and/or anti-TG antibodies." (PMID 37654906, 2023). "Most notably a rapid postpartum drop in cortisol level may precipitate thyroid autoimmunity in anti-thyroid peroxidase (TPO) antibody positive women, which could eventually produce a hypothyroid phase associated with depressive symptoms." (PMID 37868409, 2023). "TPO-Ab and TG-Ab are specific indicators of thyroid autoimmunity." (PMID 36743954, 2023). "In addition, the study found that the rs2048722 CT + TT genotype of TPO had evidently higher serum anti-thyroid peroxidase antibody (TPOAb) levels compared with CC genotype autoimmune thyroid disease patients in the Japanese population." (PMID 36737753, 2023). "We found that thyroid peroxidase, which is widely expressed in both the thyroid and breast, could be the key antigenic connection between thyroid autoimmunity and breast cancer." (PMID 37288296, 2023). "A higher TPO-Ab level at baseline corresponds with autoimmune thyroiditis." (PMID 36313770, 2022). "First, some lines of evidence had shown that adiposity increases the probability of having autoimmune thyroid diseases with an important role for a typical adipokine such as leptin as a peripheral determinant and thyroid peroxidase antibodies were more prevalent in the obese subjects." (PMID 35059043, 2022). "In addition, seleno-methionine supplementation is considered among patients with autoimmune thyroid diseases, which inhibits the production of anti-thyroid peroxidase (TPO) antibodies." (PMID 35565695, 2022). "The TPO Ab concentration is an important indicator of the existence of thyroid autoimmune disease." (PMID 35189861, 2022). "Furthermore, other thyroid antigens such as thyroid peroxidase, for instance, are involved in thyroid autoimmunity and should be addressed as well." (PMID 36499407, 2022). "Of those patients, the following had to be excluded: 15 were TPO Ab positive, 32 were taking thyroid hormones (due to autoimmune thyroid disease or after thyroid surgery), 5 thionamides, 40 were taking prednisolone > 5 mg/day, 4 amiodarone, 4 anticonvulsives, and 10 estrogens." (PMID 33575899, 2021). "Furthermore, Hashimoto encephalopathy in conjunction with psychiatric symptoms and thyroid autoimmunity must be excluded by thoroughly investigating the existence of antibodies against thyroid peroxidase (TPO) and thyroglobulin (TG)." (PMID 33026492, 2021). "Anti-TPO and anti-Tg antibodies are essential targets of the immune system in autoimmune thyroid diseases (AITDs), and increased prevalence of AITDs such as Hashimoto’s thyroiditis and Graves’s disease has been reported in pemphigus patients in several studies." (PMID 33796116, 2021). "On the other hand, higher levels of estrogen has shown to suppress T-helper cell responses type 1 (Th1), which is thought to be important for developing thyroid autoimmunity marked by increased serum concentrations of anti-thyroid peroxidase (anti-TPO) and antithyroglobulin (anti-TG) antibodies." (PMID 34113317, 2021).
autoimmune thyroid disease (continued). "Third, as levels of anti-thyroid peroxidase and anti-thyroglobulin autoantibodies were not measured in our study, we cannot determine the possible role of impending thyroid autoimmunity on the association between NAFLD with thyroid function." (PMID 34456869, 2021). "Autoantibodies against thyroid peroxidase (TPOAb) and thyroglobulin (TgAb) are commonly found in the sera of patients with autoimmune thyroid diseases (AITD), and may contribute to the abnormal thyroid functions." (PMID 32256451, 2020). "TPO-Ab is an important antibody reflecting the autoimmune thyroiditis of the human body." (PMID 32968400, 2020). "Thyroid autoimmunity (TAI) is defined as the presence of antithyroid antibodies – anti-thyroid peroxidase (TPO-Ab) and/or anti-thyroglobulin (TG-Ab) antibodies – and is the most common autoimmune condition in women of reproductive age, with a prevalence of 8–14%." (PMID 33239046, 2020). "However, as our results became robust after the exclusion of subjects positive for anti-TPO antibody, a major thyroid autoantibody, an explanation based on crosstalk between sleep and autoimmune thyroid disease would be limited." (PMID 31752113, 2019). "Thyroid autoimmunity is characterized by thyroid autoantibodies, especially anti-TPO and anti-Tg." (PMID 31467701, 2019). "In the present study, a non-smoker was defined with a value less than 50 ng/mL, the severity of smoking was categorized into four quartile groups (1st Q-4th Q), and we used the continuous variable of TPO Ab to evaluate the relationship between cigarette smoking and thyroid autoimmunity." (PMID 30862792, 2019). "Hashimoto encephalopathy is associated with very high titers of anti-thyroid peroxidase (a-TPO) antibody and autoimmune thyroiditis, while Rasmussen encephalitis is thought to be a T-cell-mediated disorder, although various antibodies are found in this disorder." (PMID 29854452, 2018). "The existence of thyroid autoimmunity (e.g. positive anti-thyroid (anti-TPO or anti-thyroglobulin) antibodies and/or borderline levels of TRAb) at the time of treatment is another risk factor at least for Graves’ disease induced by high-dose internal irradiation." (PMID 29069397, 2018). "Recognition of an autoantibody immunodominant region (IDR) on thyroglobulin and thyroid peroxidase (TPO) in spontaneous thyroid autoimmunity (humans and a mouse model) versus thyroid antibodies induced in rabbits or mice that are either restricted or not restricted to an IDR." (PMID 29326719, 2017). "TPO is also one of the major thyroid antigens in autoimmune thyroid disease." (PMID 28575127, 2017). "We found elevated anti-thyroid antibodies, both anti-TPO and anti-TG, in 29% of the population considered at-risk for developing autoimmune thyroid disease, over 80% of whom did not have optimal 25(OH)D levels (>100 nmol/L) at baseline." (PMID 29067607, 2017). "Thyroid autoimmunity was mainly attributed to TPO antibodies." (PMID 27165095, 2016). "Both antithyroglobulin and anti-TPO antibodies are valuable for screening thyroid autoimmunity." (PMID 25653881, 2015). "Hence, screening vitiligo patients for thyroid autoimmunity so as to diagnose and initiate treatment for any comorbidity with the anti-TPO Ab titre seems to be relevant as this antibody is a sensitive and specific marker of autoimmune thyroid disorders." (PMID 25653881, 2015). "Therefore, we undertook this study to look into the characteristics of vitiligo patients with thyroid autoimmunity as indicated by their anti-thyroid peroxidase antibody (anti-TPO Ab) titres." (PMID 25653881, 2015). "Assessment of anti-TPO antibodies would have provided clues for the thyroid autoimmunity status in the study population, which could have helped to explain the high rate of thyroid dysfunction." (PMID 26435714, 2015). "Thus, the sample prevalence of anti-TPO antibody positivity (thyroid autoimmunity) was estimated at 28% (95% CI for population prevalence: 19.2–36.8%)." (PMID 25653881, 2015).